NRF1 (nuclear respiratory factor 1)
Diseases named in the same sentence as NRF1 in open-access papers (continued):
Sharing a sentence is not in itself a finding about the gene and the disease.
breast carcinoma (continued). "Under hypoxic conditions, Seven in Absentia homologue 2 (SIAH2), an E3 ligase with a RING domain, is the regulator of proteasome degradation of NRF1 (Nuclear Respiratory Factor 1) and, therefore, switches TAM polarization to the tumor-promoting M2 state in breast cancer." (PMID 39544935, 2024). "We used an online database (ChIPBase v2.0) to predict the transcription factors for ZNF582-AS1, chr19:56, 393, 312-56, and 414, 800 (GRCh38/hg38), and the online tool suggested five potential candidates in breast cancer cell lines, namely CTCF, KDM5B, HIF1A, ARNT, and NRF1." (PMID 35681777, 2022). "In breast cancer cells, Nrf1 can be stabilized by OGT through O-GlcNAcylation at Ser448 and Ser451, a modification that suppresses the ubiquitin-proteasome mediated degradation of Nrf1." (PMID 33194731, 2020). "PGC-1α is a co-transcriptional regulator that induces mitochondrial biogenesis by activating transcription factors such as peroxisome proliferator-activated alpha (PPARα), estrogen-related receptor alpha (ERRα), nuclear respiratory factor 1 (NRF1), and NRF2 in breast cancer." (PMID 31552162, 2019). "Importantly, ROS can function as a signal molecule to trigger the downstream target genes of transcription factors NRF1 and NRF2 which were involved in the progression of breast cancer." (PMID 31138773, 2019). "We do not rule out the contribution of NRF1-mediated transcriptional programming of mitobiogenesis in estrogen-induced cell cycle progression during the development of breast cancer." (PMID 30486409, 2018). "Stable NRF1 overexpressing MCF10A cells, after treatment with a carcinogenic regimen of E2, were grown as mammospheres in B27 medium then flow cell sorted for the breast cancer stem cell signature CD24−/CD44+." (PMID 30486409, 2018). "HCF-1 or OGT knockdown in a breast cancer cell line, MDA-MB231 cells, also abolished the MG132-induced elevation of NRF1 protein levels, which were not necessarily correlated with NRF1 mRNA levels." (PMID 29941490, 2018).
diabetes (31 papers, 2015 to 2025). "PPARGC1A rs8192678 G/A (Gly482Ser) and NRF1 rs6949152 A/G polymorphisms have been associated with endurance athlete status, endurance performance phenotypes, and certain health-related markers of different pathologies such as metabolic syndrome, diabetes, and dyslipidemia." (PMID 32867330, 2020). "The insulin resistance and type 2 diabetes mellitus is associated with decreased expression of multiple nuclear respiratory factor-1 (NRF-1)-dependent genes that may be due to decreased expression of peroxisomal proliferator activator receptor γ coactivator (PGC1)." (PMID 30258344, 2018). "The expressions of genes such as glucose transporter protein 4 (GLUT4), myocyte enhancer factor-2 (MEF-2A), and nuclear respiratory factor-1 (NRF-1) were investigated in a palmitate-induced C2C12 cell model of type 2 diabetes mellitus." (PMID 40869081, 2025). "Collectively, impaired insulin signaling and dysregulated glucose metabolism by constitutive induction of Nrf1-Tg:MGRD results in the development of diabetes mellitus triggered by the high fat diet." (PMID 40703332, 2025). "Numerous studies showed that in diabetes there is a decrease in the expression of PGC-1α itself, as well as a decrease in the expression of genes sensitive to PGC-1α and nuclear respiratory factor-1 (NRF-1), which encode oxidative enzymes." (PMID 37833898, 2023). "Pbx1 is necessary for renal development and is involved in the activation of the nephrin promoter in the proximal tubules, while Nrf1 acts as a cytoprotective factor in cells and plays a regulatory role in diabetes by modulating the level of glutathione." (PMID 37827693, 2023). "Our results showed that STZ-induced diabetes induces histone methylation on the ERβ promoter and subsequently suppresses ERβ and its target genes, including NRF1 and SOD2, in HSCs." (PMID 33654697, 2021). "As expected, diabetes-induced down-regulation of NRF1 and TFAM mRNA expression was significantly altered by APX-115 or losartan." (PMID 29088780, 2017). "Additionally, gene array studies found a reduction in the gene expression of PGC-1α and NRF-1 in the skeletal muscle of the patients with diabetes mellitus." (PMID 33457416, 2020). "In addition, other mice expressing gain-of-function mutants of Nrf1 displayed glucose metabolic disorder, insulin resistance, diabetes and reduced body-weight." (PMID 30814566, 2019). "In addition, alogliptin restored the protein expression levels of PGC-1α, NRF-1 and Tfam that were reduced by diabetes." (PMID 30591063, 2018). "Furthermore, eight of the 17 CpG sites reside in genes (FSTL1, SORCS2, NRF1, DLC1, PPARGC1B, CHN2, NXPH1) that have prior known associations with obesity, diabetes, and the insulin pathway." (PMID 28068899, 2017). "In the diabetes-induced atrial, the agonist of PPAR-γ significantly increases mitochondrial biogenesis-related transcription factors (PGC1α, NRF1–2, TFAM) and mtDNA copy number and reduces mitochondrial ROS production." (PMID 35222272, 2022). "The expression of PGC-1 and nuclear respiratory factor-1 (NRF-1) responsive oxidative metabolism genes is reduced in muscle tissue of patients with DM2 and in normoglycemic relatives of patients with diabetes." (PMID 28191471, 2017). "The protective effects of avocado oil on mitochondrial respiration and ΔΨm during diabetes may be attributed to some of the compounds present in the oil, such as lutein as this carotenoid interacts with transcription factors counteracting mitochondrial dysfunction such as NRF-1 and PGC-1α." (PMID 26180820, 2015). "This indicates there exists an Nrf1-supporting defense for hepatocytes to counteract hypoglycemia but not promote hyperglycemia or diabetes." (PMID 40703332, 2025). "Our findings demonstrate SA elevated NRF-1 and PGC-1a expressions in gastrocnemius of STZ-induced diabetes, suggesting SA could safeguard skeletal muscle mitochondria from damage." (PMID 35432808, 2021).
diabetes (continued). "The results showed that STZ/VEH treatment decreased mRNA expression of ERβ, NRF1 and SOD2 to 68%, 39% and 42%, respectively, compared to the CTL/VEH group, while both RSV (STZ/RSV) and PTE (STZ/PTE) treatment completely restored diabetes-induced (STZ/VEH) gene suppression." (PMID 33654697, 2021).
Obesity (29 papers, 2013 to 2025). Accumulation of substantial excess body fat. "The identified association highlights the potential role of NRF1 epigenetic modifications in the pathogenesis of early-onset obesity." (PMID 40869388, 2025). "In this context, a recent investigation highlighted the racial differences in the methylation patterns of the nuclear respiratory factor 1 (NRF1), fat mass and obesity-associated (FTO), and leptin receptor (LEPR) genes among children with obesity." (PMID 40427561, 2025). "The analysis revealed a statistically significant association between hypermethylation of CpG cg01307483 in NRF1 and an increased likelihood of obesity development." (PMID 40869388, 2025). "First, pgc-1α is known to be down-regulated during the development of insulin resistance, obesity and mitochondrial dysfunction in parallel with pgc-1α target/associated genes: nrf1, nrf2 or pparα." (PMID 34959754, 2021). "It is important to note that prior studies implicated NRF1 associated with existing obesity and young Hispanic children using blood and skeletal muscle samples as well." (PMID 32059710, 2020). "Transgenic mice with Nrf1 overexpression are characterized by weight loss and protection from diet-induced obesity." (PMID 32456207, 2020). "Consistent with other studies, a higher baseline child BMI-Z during the preschool period was associated with the emergence of obesity 3 years later, but baseline methylation of NRF1 was associated with later obesity even after adjusting for baseline BMI-Z." (PMID 32059710, 2020). "Nrf1/2 activation could potentially have an influence on obesity because it is implicated in inflammation via antioxidant activity." (PMID 38139853, 2023). "Consistent with other studies, a higher baseline child BMI-Z during the preschool period was associated with the emergence of obesity 3 years later, but baseline methylation of NRF1 was associated with later obesity even after adjusting for child baseline BMI-Z." (PMID 32059710, 2020). "In mouse models of both genetic and dietary obesity, stimulation of proteasomal activity by adenovirus-mediated expression of Nrf1 or the proteasome activator PA28a to enhance proteostasis in BAT resulted in obviously improved insulin sensitivity." (PMID 40703332, 2025). "Altogether, Nrf1 emerges as a novel guardian of brown adipocyte function, providing enhanced proteometabolic quality control for thermogenic adaptation to cold or to obesity." (PMID 40703332, 2025). "Confirming the failure in mitochondrial biogenesis with obesity progression, ob/ob mice showed reduced expression in Nrf1, Tfam, and Pgc-1α." (PMID 33117273, 2020). "On the basis of this fact, Nrf1-mediated proteasome regulation is considered to be important for BAT function to adapt to either cold or obesity." (PMID 32456207, 2020). "This translates to a model-estimated 48% chance of child obesity at 36-month follow-up for a child at the 75th percentile of NRF1 baseline methylation versus only a 30% chance of obesity for a similar child at the 25th percentile." (PMID 32059710, 2020). "In the obesity reversal groups, NRF-1 was reduced by CO-28 treatment compared to both other groups (p < 0.05)." (PMID 26217498, 2014). "Furthermore, studies examining the methylation patterns of CpG islands in obese versus non-obese individuals have found differential methylation of genes such as NRF1, ADR1B, and PTPRN2, highlighting their potential as biomarkers for obesity risk." (PMID 40564006, 2025). "The current results build on the existing literature by demonstrating that DNA methylation of a critical CpG dinucleotide within the NRF1 gene in 3–5-year-old non-obese children is associated with the emergence of obesity 3 years later." (PMID 32059710, 2020).
Obesity (continued). "Thus, it is inferable that c-Myb is much likely to act as an upstream regulator of Nrf1 for transcriptionally controlling glucose metabolism, but its dysfunction leads to increased expression of Nrf1 contributable to the pathophysiology of obesity and relevant glucose metabolic dysregulation." (PMID 40703332, 2025). "For the genes NRF1, FTO, and LEPR, our study demonstrates a race-specific difference in the DNA methylation of these obesity-related genes." (PMID 36360268, 2022). "While on the other end, in EA children we saw an increase in DNA methylation of both NRF1 and FTO genes as their BMI z-score increased, implying that in the EA population, the methylation status depends more on their obesity status." (PMID 36360268, 2022). "Recent research reported that muscle mitochondrial-related genes, including NRF1, PGC1α, and UCP3, regulate insulin resistance during obesity." (PMID 32041272, 2020). "It showed that the ER-localized transcription factor nuclear factor erythroid 2-like 1 (Nrf1), a transcription factor embedded in ER membrane, is a fundamental regulator of the BAT adaptation to obesity-induced metabolic stress." (PMID 29538286, 2018). "Meanwhile, AA participants showed a negative correlation between PMR of NRF1 and obesity measures with no statistical significance." (PMID 36360268, 2022). "In this study, LT supplementation increased muscle expression of transcripts related to fatty acid oxidation (CPT1, PGC-1a, Tfam, Nrf1, SIRT1, and UCP2) without obesity-induced muscle loss." (PMID 35678694, 2022). "A previous study demonstrated that TGR5 activation inhibited oxidative stress and induced mitochondrial biogenesis by promoting SIRT1, SIRT3, and Nrf-1 expression, indicating a protective role for TGR5 inhibiting obesity-related and diabetes-related kidney disease." (PMID 33298860, 2020). "Indeed, the stimulation of proteasomal activity by exogenously expressing Nrf1 in BAT improved systemic insulin sensitivity and glucose homeostasis in genetic and dietary obesity mouse model." (PMID 29538286, 2018). "Decreased skeletal muscle Nrf-1 and Nrf-2 expression have been noted during HFD-induced obesity, and Nrf-1 is downregulated in T2D subjects compared to non-diabetic subjects." (PMID 28420087, 2017). "Other studies analyzing methylation patterns between obese and non-obese individuals have shown that genes such as NRF1, ADR1B, and PTPRN2 have differential methylation patterns, highlighting their potential as biomarkers to predict the risk of developing obesity." (PMID 40564006, 2025). "Maternal diet-induced obesity leads to increased mitochondrial potential, mtDNA content, and mitochondrial biogenesis in matured mouse oocytes, which was verified by the upregulation of mitochondrial transcription factor A (TFAM) and nuclear respiratory factor 1 (NRF1) transcripts." (PMID 36932444, 2023).
Insulin resistance (20 papers, 2010 to 2025). Increased resistance towards insulin, that is, diminished effectiveness of insulin in reducing blood glucose levels. "Importantly, Nrf1-deficient mice also displayed glucose intolerance, insulin resistance, adipocyte hypertrophy, and severe adipose inflammation." (PMID 40703332, 2025). "Similar insulin resistance also occurred in the normal-fed Nrf1-Tg:MGRD mice, with a positive correlation of increased Nrf1 expression." (PMID 40703332, 2025). "Collectively, these demonstrate that the deficiency of Nrf1 results in aberrant expression of genes related to lipolysis in WAT, leading to adipocyte hypertrophy followed by inflammation, pyroptosis, and even insulin resistance." (PMID 40703332, 2025). "This indicates that insulin resistance is triggered by Nrf1 through a distinct pathway from transcriptional repression of the insulin signaling components." (PMID 40703332, 2025). "PGC1α and NRF1 were downregulated in muscle tissue from humans exhibiting insulin resistance and T2D subjects, with a corresponding decrease in downstream OXPHOS target genes." (PMID 27917127, 2016). "It is likely that the downregulation of Pgc1 might lead to reduced Esrra, Nrf1, and Nrf2 expression, which could further impact the mitochondrial complex protein levels and establish a vicious metabolic cycle with the onset of insulin resistance." (PMID 35334815, 2022). "A study on animal models has shown that the protective effect of DHEA on high-fat-induced hepatic glycolipid metabolic disorder and insulin resistance might be achieved through the activation of the AMPK-PGC-1α-NRF-1 and IRS1-AKT-GLUT2 signaling pathways." (PMID 35741728, 2022). "PGC-1α and NRF-1 expression are reduced in diabetic and insulin-resistant human subjects." (PMID 32987623, 2020). "Mitochondrial abundance, associated to the upregulation of PGC1α and Nuclear Respiratory Factor 1 (NRF1) transcription factors resulted also in the increase of fatty acid oxidation, suggesting the favorable effect of this diet in counteracting lipotoxicity and the onset of insulin resistance." (PMID 32059421, 2020). "We hypothesize that some transcriptional pathways identified in the current analysis, including CREB, NRF-1 and SRF, may be additional novel molecular mediators of the transcriptomic phenotype associated with insulin resistance, and thus potential targets for future intervention strategies." (PMID 20369014, 2010). "In summary, EMPA activates NRF1 and SIRT7, reduces lipid accumulation, improves insulin resistance, and suppresses oxidative stress in an HFD-fed mouse model of MASLD." (PMID 40362294, 2025). "NRF1, a sister molecule of NRF2, has been recently identified as a regulator of hepatic lipid metabolism and systemic insulin resistance." (PMID 29693586, 2018). "In addition, Nrf1 transgenic mice developed insulin resistance through the suppression of insulin signaling via AKT activation in liver and skeletal muscle, implying that the efficacy of Nrf1 activation in increasing lifespan is not obvious in mammals." (PMID 32456207, 2020).
hepatocellular carcinoma (19 papers, 2016 to 2025). A malignant tumor that arises from hepatocytes. "In the other way round, aberrant accumulation of hyperactive Nrf2 in Nrf1-deficient cells (or livers) leads to further malignant transformation of human hepatocellular carcinoma (HCC)." (PMID 34268128, 2021). "Collectively, it is postulated that deficiency of Nrf1 leads to dysregulated transcription of some critical components of the Wnt/β-catenin signaling towards distinct target genes in the human hepatoma." (PMID 32273945, 2020). "The further transcriptomic analysis provides a panoramic view of the Wnt/β-catenin-dependent and -independent signaling networks, together with related responsive gene expression profiling of the Nrf1-deficient hepatoma." (PMID 32273945, 2020). "Liver-specific knockout of Nrf1 in the mouse leads to spontaneous development of non- alcoholic steatohepatitis with dyslipidemia, and then its deterioration results in hepatoma, but the underlying mechanism remains elusive to date." (PMID 30562963, 2018). "The full-length Nrf1α is processed into distinct isoforms, which together regulate genes essential for maintaining cellular homeostasis and organ integrity, and liver-specific loss of Nrf1 in mice results in spontaneous hepatoma." (PMID 27065079, 2016). "Fluorescence-activated sorting of Nrf1α−/− and Nrf1+/+ hepatoma cells revealed that Nrf1α knockout causes the cell cycle to be arrested at the G2-M phase along with the S-phase being reduced." (PMID 27065079, 2016). "In particular, the spontaneous development of NASH-based inflammation and hepatoma are resulted from severe endogenous oxidative stress and fatal defects in basal constitutive gene expression affected by its genetic instability in mouse Nrf1-deficient livers." (PMID 34268128, 2021). "However, such deficiency of Nrf1 led to downregulation of TCF4 (as a critical transcription partner of the β-catenin coactivator) in human Nrf1-silenced hepatoma xenografts and metastatic tumor tissues." (PMID 32273945, 2020). "Thereby, we speculate that activation of the Wnt/β-catenin signaling network (and/or altered expression of its dominant components) is implicated in Nrf1-deficient hepatoma development and malignant progression." (PMID 32273945, 2020). "Dysfunction of this energy sensor leads to glucose metabolism reprogramming, so to markedly aggravating the Warburg effect in Nrf1-silenced hepatoma cells, as accompanied by the resulting mitochondrial damages." (PMID 40703332, 2025). "The in-depth insights unraveled that genetic deletion of Nrf1 and Nrf2 resulted in distinct metabolism reprogramming in human hepatoma cells." (PMID 40703332, 2025). "This revealed that Nrf1 and Nrf2 behave in exactly the opposite ways: Nrf1 is more expressed in hepatocyte-like HepaRG cells, whereas the level of Nrf2 is higher in the hepatoma Huh7.5 line." (PMID 37189460, 2023). "Such morphological differences between shNrf1-expressing and control cell lines convincingly demonstrate that knockdown of Nrf1 results in the EMT process of hepatoma cells." (PMID 32273945, 2020). "Such silencing of Nrf1 resulted in malgrowth of human hepatocellular carcinoma, along with malignant invasion and metastasis to the lung and liver in xenograft model mice." (PMID 32273945, 2020). "Such knockdown of Nrf1 also enhances malignant invasion of the hepatoma and distant metastasis into the liver and lung of nude mice." (PMID 32273945, 2020). "To investigate an effect of Nrf1 on the cancer migratory behavior, we performed the in vitro scratch wound-healing assays of distinct three pairs of hepatoma cell lines expressing shNrf1 or shNC, respectively." (PMID 32273945, 2020). "This is also supported by Western blotting evidence that two major longer isoforms of Nrf1, particularly with a molecular mass of ~120 kDa, were also downexpressed in hepatoma tissues." (PMID 32273945, 2020).